IRF1 (interferon regulatory factor 1)
Diseases named in the same sentence as IRF1 in open-access papers (continued):
Sharing a sentence is not in itself a finding about the gene and the disease.
tumor (continued). "In addition, hydroxyprostaglandin, pleiomorphic adenoma gene-like 1, Ras association domain family 5, a kinase (PRKA) anchor protein 12 and deleted in colorectal cancer have been identified as IRF-1 target genes with tumor suppressor activities." (PMID 23420765, 2013). "In addition, IFN-γ and IFN-α were reported to enhance IRF-1-mediated TRAIL expression in human tumor cell lines." (PMID 24155891, 2013). "Individual studies have identified specific apoptotic gene targets but whether these make up the majority of IRF1’s tumor suppressor activity is still unknown." (PMID 25893139, 2013). "We observed that HMGA1 may inhibit the putative tumor-suppressor IRF1 (as per the interaction network) and that the miR-155 pro-oncomiR directly targeted IRF1." (PMID 24564251, 2013). "However, this molecule is also a potential downstream mediator for the tumor-suppressive activity of IRF-1." (PMID 23420765, 2013). "The involvement of IRF-1 in cell cycle regulation has been studied extensively and its tumor suppressive activity may be explained, at least in part, by its cell cycle checkpoint function." (PMID 23420765, 2013). "The mechanisms by which IRF-1 mediates tumor suppression are not well understood." (PMID 23420765, 2013). "Importantly, this data indicates that a significant function of IRF1 is the regulation of anti-cancer apoptotic pathways and this reinforces IRF1’s role as a tumor suppressor." (PMID 25893139, 2013). "Moreover, irf1 expression by the tumor was mandatory for NK cell-dependent suppression of metastases." (PMID 23269924, 2012). "Here, irf1 was implicated in the suppression of lung metastases, but not tumor spreading to the bone." (PMID 23269924, 2012). "IRF-1 was not only expressed in tumor cells, but also in some surrounding inflammatory cells." (PMID 20606993, 2010). "Thus, IRF-1 facilitates recognition of tumour cells by immune cells, ultimately resulting in an IFN-γ-dependent positive feedback loop." (PMID 20664601, 2010). "The interferon response gene IRF1 may act as a tumor suppressor by regulating the differentiation and proliferation of myeloid cells via the Stat pathway." (PMID 20098702, 2010). "Microarray analysis has elucidated that LMP2 expression dramatically influences the expression pattern of cell-cycle regulators, especially anti-oncogenic factor interferon regulatory factor 1 (IRF-1), which directly correlate to progressively worsen with the increasing stage and grade of the tumor." (PMID 19787091, 2008). "Available evidence suggests that IRF-1 may function as a tumor-suppressor gene and might induce apoptosis mediated via up-regulation of caspase 8, a key mediator frequently inactivated by epigenetic silencing in many tumors by gene hypermethylation." (PMID 17319941, 2007). "IRF-1 acts as a transcriptional activator in the interferon system and as a tumour suppressor." (PMID 14520467, 2003). "Our study provides insight into how IRF1 differentially expressed in different cell types of the same tumor may in part contribute to the pleiotropic functions observed previously in other studies, that is IRF1 displaying both antitumor and pro-tumor induction properties." (PMID 40862725, 2025). "Intriguingly, we found that PD‐L1 antibody monotherapy could induce phosphorylation of JAK1 and STAT3, thereby up‐regulating the expression of IRF1 and PD‐L1 in tumor tissues, which may also be one of the reasons why many patients are insensitive or resistant to PD‐L1 antibody monotherapy." (PMID 38953362, 2024). "In addition, IRF1 plays a role in apoptosis and tumor suppression." (PMID 39062793, 2024). "Thus, CGA might inhibit PD-L1 expression in tumor cells via suppression on the STAT1 phosphorylation-IRF1-PD-L1 pathway." (PMID 38164171, 2024).
tumor (continued). "Although the mechanisms that change the activity or amount of IRF1 in cells are complex and diverse, more detailed studies may bring us closer to defining the main pathway that regulates IRF1 activity in tumor cells and the tumor microenvironment." (PMID 38396830, 2024). "Additionally, IFN-γ induces expression of histone K (lysine) acetyltransferase 8 (KAT8), resulting in its interaction with IRF1, thereby promoting IRF1-induced chromatin acetylation and hence upregulation of PD-L1 expression in tumour cells, contributing to immune evasion." (PMID 37503572, 2023). "The high CHK1 level in the tumor may contribute to low IRF1 expression." (PMID 36765808, 2023). "Thus, IRF1 is a tumor suppressor and also plays a role in the immune response." (PMID 35406498, 2022). "In addition, we assessed whether the SUMO ligase activity of BCA2 was preserved in different cellular contexts as well as its ability to activate the IRF1 tumor suppressor." (PMID 34589482, 2021). "IRF1 may thus have opposing effects on different tumors, promoting progression of PD-L1-dependent tumors, and restricting others in which PD-L1-independent mechanisms account for tumor proliferation." (PMID 33476326, 2021). "However, the activation of IRF1 was increased in non-tumor breast cells (MCF-12F) depleted of BCA2." (PMID 34589482, 2021). "In addition, IRF-1 controls both SUMOylation and ubiquitination in tumour progression." (PMID 33076322, 2020). "One of the ways of the individual's immune response to tumor antigens is to recruit cytotoxic T cells to secrete interferon-γ (IFN-γ) in the tumor microenvironment through induction of the JAK/STAT1/interferon regulatory factor-1 (IRF-1) pathway, thus inducing PD-L1 expression." (PMID 32884946, 2020). "In addition to antiviral defense, IRF1 participates in antibacterial defense, autoimmunity, tumor immune surveillance, proinflammatory disease and immune system development, suggesting broad implications for the functional and mechanistic data described in this report." (PMID 31156620, 2019). "In addition, our microarray and bioinformatic analysis demonstrated that USP39 regulated diverse cellular signaling pathways that were involved in tumor biology, and several pivotal genes (IRF1, Caspase 8, and SP1) have been validated by quantitative real-time polymerase chain reaction." (PMID 30898977, 2019). "However, we cannot exclude that IRF1 might play additional roles in the regulation of glioblatoma resistance to bevacizumab considering the heterogeneity of the tumor microenvironment in vivo." (PMID 26362401, 2015). "Moreover, our study demonstrates that IRF1 expression in tumor cells controls BV6-stimulated secretion of several proinflammatory cytokines by tumor cells, which alters their communication with components of the immune system by triggering the recruitment of monocytes." (PMID 25501823, 2014). "Moreover, irf1 could induce tumor cell surface expression of MHC class I molecules, death receptor DR5 and adhesion molecule CD155 (ligand for DNAM-1)." (PMID 23269924, 2012). "IRF1, IRF9 and STAT1 in lymphoid cells of C1 participated in anti-tumor immune response by impacting target genes CD8A, HLA-A/E, TAP1 and PD-1." (PMID 42074110, 2026). "IRF1 (interferon regulatory factor 1), a member of the IRF family, plays significant roles in tumor suppression and immune regulation." (PMID 40177374, 2025). "MTMR2 inhibits the signaling cascade, suppressing IRF-1 expression, relieving the inhibitory effects of IRF-1 on ZEB1, and facilitating epithelial-mesenchymal transition in tumor cells." (PMID 40909948, 2025). "In conclusion, procaspase-1 and IRF-1 play crucial roles within the IFN-γ/STAT1 pathway, promoting the apoptotic death of tumor cells and thus providing viable targets for targeting malignancies." (PMID 40909948, 2025).
tumor (continued). "IRF-1 increases the migration of CD8+ T cells, NK cells, and NKT cells, and activates the secretion of IFN-γ by NK and NKT cells, thereby inducing tumor apoptosis." (PMID 40092490, 2025). "The IFN-gamma/STAT1/IRF1 axis is essential for MHC-I antigen presentation, which allows cytotoxic T cells to recognize and eliminate tumor cells." (PMID 41294799, 2025). "Disruption of the BAP1/IRF1/CIITA axis leads to a functional attenuation of MHC-II expression and MHC-II–dependent immune cell infiltration, leading to accelerated tumor growth in immunocompetent mice." (PMID 39817454, 2025). "Our previous studies supported that in addition to IRF1, TMEM230, RNASET2, and SDC2 have tumor promoting and inhibiting functions." (PMID 40862725, 2025). "Recent studies have highlighted that signaling pathways such as BRD4/IRF1, PI3K/AKT, and FAK/Src contribute to PD-L1 upregulation, facilitating tumor immune escape." (PMID 40735646, 2025). "Induction of the intratumoural cDC1 activation module that dictates anti‐tumour function is governed by enhanced activity of the transcription factors NF‐κB and IFN regulatory factor 1 (IRF1)." (PMID 40878038, 2025). "We also demonstrated that oxidative stress activates CASP8, while STING agonist upregulates IRF1 expression, subsequently inducing ZBP1 and coordinating ZBP1-CASP8 PANoptosome formation in tumor cells." (PMID 40739587, 2025). "Functionally, plasmacytoid DCs that produce IFNα stimulate the recruitment of CX3CR1+ MDSCs through hepatocyte IRF1/CX3CL1 signaling, resulting in tumor recurrence after hepatectomy in HCC." (PMID 40470380, 2025). "IRF1, IRF2, IRF4, IRF5, IRF7, and IRF8 were positively correlated with the stromal and immune scores and negatively correlated with tumor purity." (PMID 39897128, 2025). "In terms of function, plasmacytoid DCs that produce IFNα stimulate the recruitment of CX3CR1+ MDSCs through hepatocyte IRF1/CX3CL1 signaling, subsequently promoting tumor recurrence following hepatectomy in HCC." (PMID 40470380, 2025). "The study of IRF1 and IFN-β roles in M1 polarization of macrophages and their anti-tumor functions demonstrated that these two factors regulate IRF5 expression, contributing to M1 polarization." (PMID 39941858, 2025). "IRF1, in turn, upregulates MHC-I gene expression, ensuring the presentation of tumor antigens to T cells." (PMID 41294799, 2025). "What’s more, DNA damage can enhance the expression of PD-L1, facilitating tumor evasion and hindering the recruitment of CD8 T cells, partly by activating ATM/ATR/CHK1 pathway through IRF1 signaling." (PMID 40740769, 2025). "The inferred activity of IRF1 and STAT1 regulons were positively correlated with the sum of normalized APPG expression in tumor cells (Pearson R = 0.78, p-value = 0)." (PMID 40894019, 2025). "This indicates that the interplay among IRF1, IFN-β, and IRF5 is crucial for the M1 polarization of macrophages and their anti-tumor activities, providing potential targets for cancer therapy." (PMID 39941858, 2025). "MiR-383 exerts its effects by targeting interferon regulatory factor-1 (IRF1), a tumor suppressor, leading to inhibition of proliferation through G1-phase arrest and induction of apoptosis." (PMID 38625593, 2025). "Downregulation of tumor suppressors, such as FOXO3 and IRF1, and increased FOXP3 and pAKT1, were observed." (PMID 40924302, 2025). "We show here that CGA suppressed tumor cell PD-L1 expression induced by IFN-γ, through inhibiting IFN-γ/JAK/pSTAT1/IRF1/PD-L1 pathway." (PMID 38164171, 2024). "In contrast, disruption of this connection between IRF1 and KAT8 resulted in decreased cellular PD-L1 levels, decreased tumor mass, and increased numbers of tumor-infiltrating CD8+ T cells." (PMID 38396830, 2024). "IFN-γ released by T cells, is a crucial regulator inducing PD-L1 expression in tumor cells, where the IFN-γ/JAKs/STATs/IRF1 axis is the main pathway to induce and maintain PD-L1 expression in malignancies." (PMID 38762484, 2024).
tumor (continued). "It has been reported that the transcriptional factors p-NF-κB and/or p-STAT1 can be activated by IFN-γ and promote IRF1 expression, which promotes IDO1 expression in IFN-γ-treated human tumor cells." (PMID 38540186, 2024). "NR4A1 was markedly upregulated in tumor-infiltrating NK cells, which reduced the efficacy of anti-PD-1 therapy through modulation of the IFN-γ/p-STAT1/IRF1 signaling pathway, leading to dysfunctional tumor-infiltrating NK cells." (PMID 38999981, 2024). "IRF1 increased CXCL10 gene transcription and exhibited antiproliferative and pro-apoptotic effects on tumor cells, presumably by activating the CXCL10/CXCR3 autocrine pathway." (PMID 38396830, 2024). "Inhibition of IGF2BP3-induced expression of IRF1 activates interferon (IFN) signaling pathway and then exerts its anti-tumor effect." (PMID 38448411, 2024). "In a word, the roles of IRF1, IRF2, and IRF3 in HCC are complex and bidirectional, exhibiting both tumor-promoting and anti-tumor effects." (PMID 39384770, 2024). "These core genes contained at least 8 (PPP2R2A, CXCL10, CXCL11, GBP1, IRF1, RARRES3, STAT1, and TAP1) previously identified regulators of tumor progression and distant metastasis." (PMID 38545852, 2024). "IFNγ is released by immune cells in the tumor microenvironment and tumor cells respond by activation of JAK-STAT signaling, leading to IRF1 activation." (PMID 39237877, 2024). "The tumor suppressors ETV6, CEBPA, IRF8, and IRF1 are among the lineage-controlling master TFs found in CD141-positive monocytes enriched with SE-associated genes upregulated by cortistatin A." (PMID 37501079, 2023). "Specifically, it has been shown in several cancer cell lines that osteopontin, a secreted protein whose expression has been coupled to tumor progression and metastasis, induces HOTAIR expression inhibiting the expression of IRF1 via PI3K/AKT pathway." (PMID 37308974, 2023). "We made similar observations for Stat1 and other STAT1 target genes including Irf1, Cxcl10, and Cxcl11, which suggested that PARP14 was induced specifically in IFNγ-inflamed tumours but independently of α-PD-1." (PMID 37752135, 2023). "Being originally identified as a tumor suppressor, it is somewhat surprising that PLAAT4 is also one of the common downstream targets of IRF1 and IFN signals." (PMID 37063830, 2023). "STAT1 then upregulates IRF1 to repress the expression of SLC7A11 and SLC3A2, the two subunits of the glutamate-cystine antiporter system xc-, to limit tumor cell cystine uptake, resulting in tumor cell lipid peroxidation and death." (PMID 36672246, 2023). "We also found that IRF1, IRF3, IRF4, IRF5 and IRF7 were significantly higher in tumor stage III/IV or grade 3/4 compared with tumor stage I/II or grade 1/2, whereas the expression level of IRF6 was lower in tumor stage III/IV or grade 3/4." (PMID 37182129, 2023). "We assessed IRF1 as a reportedly tuneable ISG with antiproliferative and tumour-suppressor function." (PMID 38066598, 2023). "Selected genes are reflecting main anti-tumor immune pathways, such as Th1 signaling (IFNG, TBX21, CD8A/B, IL12B, STAT1 and IRF1), Th1 chemoattraction (CXCL9, CXCL10 and CCL5) and cytotoxic functions (GNLY, PRF1, GZMA, GZMB and GZMH)." (PMID 37726776, 2023). "ATXN3-induced Pd-l1 transcription was promoted by tumor microenvironmental factors, including the inflammatory cytokine IFN-γ and hypoxia, through protection of their downstream transcription factors IRF1, STAT3, and HIF-2α." (PMID 38038129, 2023). "Another study revealed that IRF1 increased CD8+ T cells, NK and NKT cells migration, and activated IFN-γ secretion in NK and NKT cells to induce tumor apoptosis through the CXCL10/CXCR3 paracrine axis in HCC." (PMID 37051536, 2023).
tumor (continued). "Additionally, western blot analysis demonstrated that the expression of IRF1 and pTBK, both critical signaling elements for transcription of interferons and inflammatory cytokines, was enhanced in the circCsnk1g3- and circAnkib1-silenced tumor cells, in line with the RNA-level data." (PMID 36433954, 2022). "Up-regulation of ten DEGs in PAAD tumor is in concordance with the up-regulation of master regulators CTCF, IRF1, and KLF4, while POLR2A and STAG1 remain unchanged." (PMID 35453789, 2022). "Whereas IRF1 activation was increased in HEK293T and ER+ MCF-7 cells overexpressing HA-BCA2, its activation was decreased in ER– MDA-MB-231 and non-tumor MCF-12F cells." (PMID 34589482, 2021). "Confirming previous analyses, MUC1 expression was detectable in TNBC tumor cell populations, along with STAT1 and IRF1." (PMID 33495298, 2021). "Although an ortholog of protein kinase R (PKR), an IRF1-regulated, IFN-inducible protein with tumor-suppressor activity, exists in zebrafish, the tumor-suppressor potential of IRF1 remains uncertain among lower vertebrates." (PMID 33476326, 2021). "In this experiment, lycopene managed to enhance IFNβ, IFNγ, IRF1, IRF7, CXCL9, CXCL10 while suppressing IL-4, IL-10, DMNT3a, methylation of IRF1, IRF7 promoters and most importantly, the tumor volume." (PMID 34202203, 2021). "Interferon regulatory factor 1 and 9 (IRF1 and IRF9) are transcriptional regulators of interferon-B and tumor suppressors of IFN-inducible genes." (PMID 32101552, 2020). "In PBRM1 wild-type tumors, IFNγ induces the tumor cell-autonomous expression of STAT1, IRF1 and of chemoattractive chemokines, which enhances T-cell infiltration and activation." (PMID 32358509, 2020). "Eight co-expressed genes (PSMB8, PSMB9, PSMB10, PSME2, TAP1, IRF1, FBOX6, ETV7) were identified as CD8+ T cell-related genes that promoted infiltration of CD8+ T cells, and were enriched in the MHC class I tumor antigen presentation process." (PMID 33330025, 2020). "Immunohistochemical staining for IRF1 and Ki67 in serial sections of 4T1 tumors validated the presence of IRF1+ and Ki67+ cells within the same region of these tumors, suggesting that activation of interferon signaling could be a driver for tumor growth in this model." (PMID 32840210, 2020). "New signaling pathways of interferon regulatory factors 1 (IRF-1) and 2 (IRF-2) and interleukin (IL)-1 family, IL-6, IL-11, IL-18, and interferons (IFNs) have been found within tumor microenvironments." (PMID 32887217, 2020). "Other candidates such as EGR1, RUNX2, STAT1, TRAP2, IRF1 and USF1 have been experimentally validated as drug targets, metastasis promoter or tumor growth enhancers, see19–24." (PMID 31857653, 2019). "FFPE sections were macrodissected to enrich for tumor for quantitative assessment of CD274 (PD-L1), PDCD1LG2 (PD-L2), CD8A, and IRF1 by RT-qPCR multiplex mRNA panel." (PMID 31533832, 2019). "Significant correlations among the protein levels of PDL1, eIF2α, and ATF4 and between those of IRF1 and PDL1 were observed in the tumor tissues of both subgroups and in the normal tissue of SCC." (PMID 30305853, 2018). "The protein levels of IRF1, eIF2α, ATF4, and PDL1 in the tumor tissues of the all subject group formed a cluster in the hierarchical cluster dendrograms." (PMID 30305853, 2018). "These were IRF1 and GBP5; genes related to transcriptional regulation, tumor response, inflammation, and innate immunity." (PMID 30408130, 2018). "The correlations among the protein levels of IRF1, PDL1, eIF2α, and ATF4 were significant in the tumor tissues, and similar patterns were found in the normal tissues except those between eIF2α and ATF4." (PMID 30305853, 2018). "Together, this study adds a new tumor suppression mechanism by which XAF1 functions as a coactivator of stress-inducible transcription factors, such as IRF-1." (PMID 30042418, 2018).